CDA (cytidine deaminase)
Description:
This enzyme scavenges exogenous and endogenous cytidine and 2'-deoxycytidine for UMP synthesis.
Synonyms: CDD
Tractability: Small molecule: an approved drug acts on it; a structure with a bound ligand is known; a high-quality ligand is known; it belongs to a druggable protein family. Antibody: its Gene Ontology location is reachable by antibodies, with high confidence. PROTAC: ubiquitination databases record sites on it; a small molecule that binds it is known.
Target class: Enzyme; Hydrolase
Safety:
Unwanted effects reported when the protein is acted on. In parentheses: how it was acted on, where the effect was seen, and who reports it.
neutropenia (source: ClinPGx)
clearance of gemcitabine (source: ClinPGx)
death (source: ClinPGx)
diarrhea or dehydration (source: ClinPGx)
drug toxicity (source: ClinPGx)
grade 3 hand-foot syndrome (source: ClinPGx)
hyperbilirubinemia (source: ClinPGx)
incidence of adverse events, hand-foot syndrome (source: ClinPGx)
levels of toxicity (source: ClinPGx)
nausea (source: ClinPGx)
survival time (source: ClinPGx)
Gene: Protein-coding gene on chromosome 1 (20,588,932 to 20,618,908, forward strand). Ensembl gene ENSG00000158825.
Subcellular location (Human Protein Atlas): Nucleoplasm
Pathways (Reactome):
Immune System: Neutrophil degranulation
Metabolism: Pyrimidine salvage
Gene Ontology:
Molecular function: cytidine deaminase activity; identical protein binding; nucleoside binding; protein binding; protein homodimerization activity; zinc ion binding; hydrolase activity
Biological process: CMP catabolic process; dCMP catabolic process; cytosine metabolic process; deoxycytidine catabolic process; pyrimidine-containing compound salvage; uridine biosynthetic process; cellular response to external biotic stimulus; pyrimidine ribonucleoside monophosphate metabolic process; pyrimidine ribonucleotide metabolic process; UMP salvage
Cellular component: cytosol; extracellular region; ficolin-1-rich granule lumen; secretory granule lumen; tertiary granule lumen; cytoplasm
Genetic constraint (gnomAD): Loss-of-function variants: 7 observed, 13.77 expected, observed/expected ratio (o/e) 0.51, 90% interval 0.29 to 0.95. The upper end of that interval is the gene's LOEUF score, 0.95, which puts it in group 4 of 6, group 1 being the genes least tolerant of losing a copy. Missense variants: 148 observed, 172.88 expected, observed/expected ratio (o/e) 0.86, 90% interval 0.75 to 0.98. Synonymous variants: 53 observed, 70.06 expected, observed/expected ratio (o/e) 0.76, 90% interval 0.61 to 0.95.
Homologues: Orthologues: chimpanzee CDA (100% identical), pig CDA (84% identical), mouse Cda (82% identical), rat Cda (82% identical), guinea pig CDA (80% identical), macaque CDA (78% identical), dog CDA (77% identical), zebrafish cdab (65% identical), tropical clawed frog cda (64% identical), zebrafish cdaa (61% identical), rabbit CDA (60% identical), Caenorhabditis elegans cdd-2 (45% identical), and 1 more.
Diseases named in the same sentence as CDA in open-access papers:
CDA is named in the same sentence as 111 diseases in open-access papers, as found by Europe PMC text mining. Sharing a sentence is not in itself a finding about the gene and the disease. The quoted sentences say what the papers report.
pancreatic cancer (41 papers, 2007 to 2026). "Overexpression of cytidine deaminase (CDA) is also observed in pancreatic cancer cells along with MRP-1 (multidrug resistance-associated protein) transporter responsible for causing an efflux of clinically relevant drugs." (PMID 38107772, 2021). "Moreover, CDA is reported to be overexpressed in pancreatic cancer and closely associated with the effect of Gemcitabine in PDAC." (PMID 34930261, 2021). "This suggests that higher response rate and survival benefits observed in pancreatic cancer patients treated with the combination of gemcitabine plus nab-paclitaxel are possibly linked to reduced CDA levels, reduced deamination of gemcitabine and, thereby, resultant enhanced activity." (PMID 29144412, 2017). "Here, we performed a prospective clinical trial in gemcitabine-treated patients with resected pancreatic cancer which aimed at investigating the impact of CDA deficiency on the occurrence of toxicities and on pharmacokinetics, but also to better understand CDA genotype-phenotype relationships." (PMID 26308942, 2015). "Similarly, low plasma CDA activity and heterozygous CDA*3 were also significantly associated with prolonged overall survival in advanced pancreatic carcinoma." (PMID 22616006, 2012). "Conversely, METTL14 is overexpressed in gemcitabine-resistant pancreatic cancer cells and mediates the up-regulation of cytidine deaminase, promoting gemcitabine resistance in pancreatic cancer." (PMID 40483535, 2025). "This study discovered that in comparison to normal tissue, CDA expression was highly elevated in colon, gastric and esophageal malignancies, as well as strongly up-regulated in pancreatic tumors." (PMID 40011298, 2025). "CDA targeting in pancreatic cancer cell lines led to reduced tumor growth, weight and total regression after treatment aimed at the programmed cell death protein 1 receptor (PD-1) immune checkpoint protein." (PMID 40011298, 2025). "Albumin-conjugated nanocarriers of Paclitaxel have improved the efficacy of the first-line pancreatic cancer drug Gemcitabine by inhibiting the tumor stroma and suppressing the expression of the gemcitabine-inactivating enzyme cytidine deaminase." (PMID 38375157, 2024). "Using the Xena PanCAN-GTex platform (and selecting for The Cancer Genome Atlas (TCGA) bulk RNA-seq datasets only), CDA expression was strongly upregulated in pancreatic tumor versus normal tissue." (PMID 38844817, 2024). "We discovered that shorter overall survival in patients with pancreatic cancer was substantially correlated with increased CDA expression." (PMID 37240761, 2023). "High levels of CDA have been related to the development of gemcitabine resistance in breast and pancreatic tumor cells." (PMID 37108401, 2023). "Upregulated METTL14 hampers the attenuation of cytidine deaminase (CDA) transcript, enhances its stability, and induces chemotherapy resistance of pancreatic cancer cells." (PMID 34904301, 2022). "We found that DCK was decreased and CDA was overexpressed in gemcitabine resistant tumor samples and pancreatic cancer cells." (PMID 34458141, 2021). "A study conducted on pancreatic cancer patients with gemcitabine treatment demonstrated a correlation between CDA activity and chemoresistance and concluded that patients with 6U/mg or higher of CDA activity showed progression of disease by five-fold or more." (PMID 35582220, 2020). "A recent study demonstrated that activated platelets released ADP and ATP and promoted pancreatic cancer cell survival via increasing cytidine deaminase expression." (PMID 32393273, 2020). "CDA expression has been correlated with OS in pancreatic cancer patients, as well as preclinical responses to gemcitabine." (PMID 29144412, 2017). "Recently, CDA was identified as a regulator of cell proliferation and chemoresistance in breast and pancreatic cancer." (PMID 26745821, 2016).
pancreatic cancer (continued). "Regarding Gem, reduced phosphorylation by dCK was identified to be a key process for acquiring Gem resistance over other processes via ENT1 and CDA in a pancreatic cancer cell line." (PMID 26622566, 2015). "Conversely, we have shown that UM pancreatic cancer patients (i.e., CDA activity > 6 U/mg) were 5-times more likely to have progressive disease upon gemcitabine intake, as compared with patients with normal CDA status." (PMID 26308942, 2015). "In this study, CDA expression was measured in three different pancreatic carcinoma cell lines (Panc-1, MIAPaCa-2, and BxPC-3)." (PMID 22616006, 2012). "Mycoplasma and other Gammaproteobacteria found in pancreatic cancers was recently shown to metabolize gemcitabine, a pyrimidine nucleoside, using a long isoform of cytidine deaminase, and it is possible that this enzyme has additional unrecognized effects on DNA repair or pyrimidine metabolism." (PMID 40761254, 2025). "Interestingly, pancreatic cancer cells can evade ER stress-induced apoptosis through up-regulation of specific proteins, such as Mucin 1 and cytidine deaminase which are involved in pyrimidine metabolic pathway." (PMID 40655023, 2025). "Using CRISPR-Cas9, the authors genetically targeted CDA in mouse pancreatic cancer cell lines." (PMID 40011298, 2025). "In addition, Ralstoniapickettii belongs to class Gammaproteobacteria, which has been reportedto carry long cytidine deaminase that can metabolize the chemotherapy druggemcitabine, thereby inducing chemoresistance in pancreatic cancer." (PMID 39387592, 2024). "Cytidine deaminase, an enzyme produced by gammaproteobacteria, can metabolize gemcitabine and has been hypothesized to inhibit pancreatic tumor response to chemotherapy." (PMID 39795998, 2024). "Compared to normal tissues, pancreatic cancer tissues had a considerably higher amount of CDA mRNA." (PMID 37240761, 2023). "CDA can also be secreted into the extracellular space, and although intracellular CDA is the main determinant of gemcitabine sensitivity in cell lines, even with just pancreatic cancer cell lines, secreted CDA still accounts for a substantial amount of gemcitabine metabolism." (PMID 34830914, 2021). "miRNAs also regulate CDA expression; miR-484 directly inhibits CDA translation by targeting CDA 3’UTR and induces chemoresistance in breast cancer cells, and decreased expression of miR-608 correlates with upregulation of CDA to induce chemoresistance in pancreatic cancer cells." (PMID 35582220, 2020). "Albumin-conjugated paclitaxel (nab-paclitaxel) was shown to reduce the CDA protein by producing reactive oxygen species in a mouse pancreatic cancer model; this evidence may explain the usefulness of gemcitabine plus nab-paclitaxel (GnP)." (PMID 35582220, 2020). "Combination treatment with nab-paclitaxel increases intratumoral gemcitabine levels in mouse models of pancreatic cancer, which has been attributed to stromal disrupting effects of nab-paclitaxel, or a marked decrease in the levels of cytidine deaminase, the primary gemcitabine metabolizing enzyme." (PMID 26231955, 2015). "Overexpression of circFARP1 in CAFs confers GEM resistance in pancreatic cancer cells by enhancing the expression and secretion of LIF in CAFs, thereafter activating the STAT3 signaling pathway and increasing the expression of several GEM resistance-associated factors, including ABCC2, CDA and SOX2." (PMID 35045883, 2022). "As a result, a combination regimen of THU and gemcitabine might be a more effective therapy than previously believed for pancreatic carcinoma since THU works as a CDA inhibitor, as well as an inhibitor of cell growth in some types of pancreatic carcinoma cells." (PMID 22616006, 2012). "Gemcitabine addresses pancreatic cancer by impacting WIF-1, the Wnt signaling pathway inhibitor 1, PHD finger protein 10, and cytidine deaminase (CDA)." (PMID 39791162, 2025).
pancreatic cancer (continued). "First, we evaluated the expression of NT5C1A, CDA and DCK in KPC mice and OTM by analyzing the expression of GME in bulk pancreatic cancer tissue." (PMID 38744194, 2024). "They reported that METTL14 was overexpressed in gemcitabine-resistant pancreatic cancer cells and p65 (a transcription factor) promoted the expression of METTL14 and subsequently upregulated cytidine deaminase (CDA), a gemcitabine inhibitor." (PMID 37264402, 2023). "We analyzed the mRNA expression levels of the MBOAT2/CDA/LPCAT2/B4GALT5 genes in PACA patient samples and pancreatic cancer cells." (PMID 37240761, 2023). "We further determined that the circFARP1/LIF axis remarkably increased the expression of GEM resistance-related genes, such as ABCC2, CDA, and SOX2, and induced GEM resistance in pancreatic cancer cells." (PMID 35045883, 2022). "For example, overexpression of miR-608, which targets ribonucleotide reductase large subunit M1 (RRM1) and cytidine deaminase (CDA), decreased the viability of the gemicitabine-resistant MIA-PaCa-RG4 and AsPC-RG2 pancreatic cancer cells." (PMID 32625096, 2020). "The long-type isomer of cytidine deaminase (CDD) in these bacteria can modify the chemical structure of the chemotherapy drug gemcitabine, rendering it inactive and thereby promoting chemotherapy resistance in pancreatic cancer." (PMID 41602751, 2026). "It is proposed that MBOAT2, CDA, LPCAT2 and B4GALT5 expression may promote the onset and progression of pancreatic cancer." (PMID 37240761, 2023). "Gene expression profile analysis and further experiments showed that circFARP1 conferred GEM resistance by enhancing LIF expression and secretion in CAFs, thereafter increasing the expression of ABCC2, CDA and SOX2 by activating the STAT3 signaling pathway in pancreatic cancer cells." (PMID 35045883, 2022). "Interestingly, in pancreatic cancer, miR-608 is downregulated, and miR-608 can target ribonucleotide reductase M1 (RRM1) and cytidine deaminase (CDA) and control gemcitabine resistance." (PMID 35387124, 2022). "In two studies, a higher response to treatment with gemcitabine in pancreatic cancer patients was correlated with low circulating CDA activity, however, the results were not the same in a later multicenter prospective trial in which 120 patients received treatment with gemcitabine." (PMID 36309754, 2022). "The mRNA levels of MBOAT2, CDA, LPCAT2 and B4GALT5 were significantly higher in PACA cells than in normal human pancreatic duct epithelial cells, implying that the high expression levels of these four genes may promote the development and progression of pancreatic cancer." (PMID 37240761, 2023). "This study showed that gemcitabine was protected from rapid deactivation by cytidine deaminase and increased the in vitro cytotoxicity in L3.6pl and BXPC-3 pancreatic cancer cells compared to non-conjugated gemcitabine." (PMID 39766323, 2024).
breast carcinoma (19 papers, 2014 to 2025). "Recently, A3A has been identified as a major source of cytidine deaminase-induced mutations in breast cancer, which has emphasized the importance of understanding what mechanisms influence A3A abundance in cancer cells." (PMID 38155930, 2023). "We analyzed CDA activity and expression in blood samples from breast cancer (BC) patients with a suspected predisposition to the disease, and in healthy controls." (PMID 35982128, 2022). "Experimentally, A3B was shown to be over-expressed, the primary source of cytidine deaminase activity, and a source of mutation in a panel of breast carcinoma cell lines, indicating a role for this enzyme in breast cancer mutagenesis." (PMID 28117753, 2017). "Atypical expression of AID and CSRnc in non‐lymphoma tumor cells could result in cytidine deaminase‐mediated kataegis, a mutation process frequently observed in breast cancer." (PMID 39144468, 2024). "In addition, specific mutation signals and the role of APOBEC3B, as a cytidine deaminase, have been established in the occurrence and development of cervical cancer, breast cancer, lung cancer, and other cancers." (PMID 36203448, 2022). "It is tempting to speculate that the cytidine-deaminase-associated mutational landscapes in breast cancer might be enriched at ER/A3B binding regions." (PMID 26411678, 2015). "We analyzed CDA mRNA and protein activity levels in blood samples from BC patients with a suspected predisposition to breast cancer (BC), and from healthy volunteers as controls, to determine whether a constitutive CDA deficiency might underlie some breast cancers." (PMID 35982128, 2022). "Signature_2 is more prevalent in luminal B-like disease breast cancers with a similarity of 0.729 to COSMIC_2, associated with “APOBEC Cytidine Deaminase”." (PMID 38380359, 2024). "Increases in A3A cytidine deaminase activity generally corresponded with changes in A3A transcript levels across the retinal pigment epithelial, breast cancer and multiple myeloma cell lines tested." (PMID 38155930, 2023). "A3A provides the majority of cytidine deaminase activity in whole cell extracts containing RNA [which inhibits APOBEC3B (A3B) activity] from a variety of breast cancer cell lines." (PMID 38155930, 2023). "Our findings identify A3A as a major source of cytidine deaminase activity in breast cancer cells and possibly a prominent contributor to the APOBEC mutation signature." (PMID 31841499, 2019). "Taken together, our cytidine deaminase activity assays in breast cancer cell extracts, suggests that A3A is the dominant cytidine deaminase active on hairpin substrates in the presence of RNA, while in the absence of RNA, A3B dominates." (PMID 31841499, 2019). "A preliminary analysis of CDA activity in the serum of the very few BC patients who had undergone no treatment other than surgery suggested that the increase in CDA activity might be due to the breast cancer itself." (PMID 35982128, 2022). "A previous study found that miR-484 could inhibit CDA and suppress the proliferation of breast cancer cells." (PMID 30002603, 2018). "In BS fibroblasts, HeLa cells and breast cancer cell lines and tissues, low levels or absence of CDA were associated with higher levels of Tau mRNA and protein, consistent with a physiological mechanism regulating the levels of both proteins." (PMID 28947735, 2017). "Moreover, FOXO3a transactivates miR-484 expression, which might downregulate cytidine deaminase, resulting in enhanced sensitivity of breast cancer to gemcitabine." (PMID 39930542, 2025). "Could the increase in CDA activity in the serum of BC patients be due to the breast cancer itself?" (PMID 35982128, 2022). "In addition, A3A often provides the majority of cytidine deaminase activity and APOBEC-signature mutations in breast cancer cell lines (even in the presence of A3B and A3H-I) in part due to its stronger cytidine deaminase activity and unique resistance to RNA inhibition." (PMID 34697369, 2021).
breast carcinoma (continued). "Therefore, we hypothesized that the upregulation of CDA expression is one mechanism by which LKB1 reduces sensitivity to gemcitabine in breast cancer cells." (PMID 25295095, 2014). "However, even though we cannot yet determine whether an increase in CDA activity/expression in the blood of patients with breast cancer is of clinical/therapeutic interest for patients, we believe that our results are highly original and open up interesting perspectives for new functional studies." (PMID 35982128, 2022). "Finally, we present preliminary data, based on the analysis of CDA activity in the serum of a very small number of BC patients who underwent surgery but not RT, CT or HT, raising the possibility that the increase in CDA activity may be due to the breast cancer itself, rather than RT." (PMID 35982128, 2022). "The negative correlation between CDA and MAPT transcript levels was significant in cancers of several tissues, including breast cancer, papillary, and clear cell kidney carcinomas, prostate adenocarcinoma, and pheochromocytoma and paraganglioma." (PMID 28947735, 2017).